IL2 (interleukin 2)
Diseases named in the same sentence as IL2 in open-access papers (continued):
Sharing a sentence is not in itself a finding about the gene and the disease.
HIV-1 infection (continued). "Our findings reveal a novel pathway that the HIV-1 infection-induced suppression of the let-7i/IL-2 axis contributes to CD4+ T cell death." (PMID 29426337, 2018). "PBLs were isolated from healthy donors and pre-activated with IL-2 for at least 48 h before the experiment to allow HIV-1 infection." (PMID 29720939, 2018). "Recent studies have demonstrated decreased IL-2 expression in primary Th cells with latent HIV-1 infection even after activation of the cells with mitogens." (PMID 29354130, 2017). "Given that let-7i is a positive regulator of IL-2 gene transcription, it is possible that suppression of let-7i contributes to the CD4+ T cell death caused by HIV-1 infection." (PMID 27145859, 2016). "We observed the expected elevation of CD4+ T cell apoptosis concomitant with HIV-1 infection, which is consistent with the decreased IL-2 level." (PMID 27145859, 2016). "Taken together, the let-7i induced IL-2 has a protective effect against CD4+ T cell apoptosis, especially protects cells from the cytotoxicity caused by HIV-1 infection." (PMID 27145859, 2016). "IL-2-secreting CD4+ T cells detected by flow cytometry (FCM) were also significantly reduced during HIV-1 infection." (PMID 27145859, 2016). "The silencing of IL-2 by siRNA diminished the let-7i-mediated resistance of CD4+ T cells to HIV-1 infection-induced apoptosis." (PMID 27145859, 2016). "In summary, our study indicates that HIV-1 infection leads to the downregulation of the let-7i/IL-2 axis and contributes to CD4+ T cell death." (PMID 27145859, 2016). "We infected primary human CD4+ T cells with HIV-1NL4-3 virus and found that, along with the infection, the levels of mature let-7i miRNA in CD4+ T cells decreased gradually, which is in agreement with the IL-2 expression change during HIV-1 infection." (PMID 27145859, 2016). "A previous study reported that highly active antiretroviral therapy combined with IL-2 can provide beneficial effects in the treatment of early HIV-1 infection." (PMID 26077233, 2015). "Serum levels of IL-2 are decreased during HIV-1 infection and decreased production of IL-2 by T-cells, the main IL-2 producing cells, has been shown in healthy individuals with advanced age." (PMID 25213015, 2014). "Following ex vivo culture in media containing IL-2 stimulation alone, the proportion of degranulating NK cells was elevated during primary HIV-1 infection compared to prior to HIV acquisition, (p = 0.006)." (PMID 23326405, 2013). "During HIV-1 infection, cytotoxic NK cell responses evaluated after IL-2 stimulation alone, or after co-culture with 721 cells, were impaired (p = 0.006 and p = 0.002, respectively)." (PMID 23326405, 2013). "For instance, bystander activation occurs mainly through cytokines, including interferon-α/β, IL-2 and IL-15, which are all increased in HIV-1 infection and represent independent and accurate predictors of disease progression." (PMID 23382678, 2013). "Treg cell depletion using the IL-2–toxin fusion protein denileukin diftitox prior to HIV-1 infection in humanized mice has been shown to reduce plasma viremia on days 4–10 p.i.." (PMID 21364928, 2011). "It has been reported that duration of anti-CD3/28 and IL-2 signaling is important for efficient HIV-1 infection of human T cells." (PMID 18446227, 2008). "Overall, we demonstrate that GZB+ CD4 T cells are prevalent in the colon during chronic HIV-1 infection and may emerge following interactions with translocated bacteria in an IL-2 and MHC Class II-dependent manner." (PMID 35258402, 2022). "The attributes of CD73+ CD4+ T cells, particularly IL-2 production and proliferative capacity in response to recall antigens, are notably deficient in the CD4+ T cell function of the vast majority of subjects with HIV-1 infection soon after infection." (PMID 33477692, 2021).
HIV-1 infection (continued). "Although our group has recently provided evidence that the increased production of tryptophan-related catabolite kynurenine during primary HIV-1 infection affected IL-2-induced STAT5 activation in Mem, interfering with this disturbance was not sufficient to restore proper cell survival." (PMID 31658294, 2019). "Numerous studies have shown that ART and in vivo administration of IL-2 could partially restore NK cell distribution and function in HIV-1 infection." (PMID 31379845, 2019). "The impaired abilities of CD56+ T cells to secret IL-2 may contribute to weaken NK cell-mediated ADCC function in HIV-1 infection." (PMID 31379845, 2019). "HIV-1 infection-induced CD32 expression in PHA/IL-2 activated CD4+ T cells." (PMID 30013105, 2018). "During chronic progressive HIV-1 infection, there is also progressive loss of CD4+ lymphocytes and perturbation of immune function, which may be due to the dysregulation of IL-2 and other cytokines through unrevealed pathways." (PMID 27145859, 2016). "In the control group, the let-7i mimic still significantly decreased the HIV-1 infection-induced apoptosis of CD4+ T cells, but when IL-2 was knocked down, the apoptosis caused by HIV-1 infection was not rescued by let-7i overexpression." (PMID 27145859, 2016). "Collectively, our results have shown that HIV-1 infection could induce the suppression of both IL-2 and let-7i expression." (PMID 27145859, 2016). "Accordingly, we hypothesized that HIV-1 infection could reduce the IL-2 expression by downregulating let-7i miRNA, leading to the death of both infected and bystander activated CD4+ T cells." (PMID 27145859, 2016). "We first confirmed the effects of IL-2 in maintaining CD4+ T cell survival in HIV-1 infection." (PMID 27145859, 2016). "Our data show that HIV-1 infection could decrease the IL-2 expression of CD4+ T cells in vitro." (PMID 27145859, 2016). "As a result of HIV-1 infection, the production of IL-2-expressing memory CD4+ T cells is reduced, leading to decreased IL-2 levels." (PMID 37608956, 2023). "The HIV-1 infection of TZM-bl cells did have an effect; we observed decreased levels of IL-2 and CCL2 and increased levels of IL-6 and IL-8." (PMID 36432041, 2022). "In HIV-1 infection, IFN-γ single positive mycobacteria-specific CD4+ T cells were decreased, while the frequency of polyfunctional cells (IFN-γ+IL-2+TNF-α+) remained unchanged." (PMID 27865393, 2016). "Because IL-2 is a very important cytokine for maintaining activated CD4+ T cell survival and proliferation, we examined the depletion of CD4+ T cells during HIV-1 infection by both cell morphology and Annexin V staining assay." (PMID 27145859, 2016). "HIV-1 infection of cultured human cardiomyocytes (CM) and peripheral blood mononuclear cells (PBMCs), activated with phytohemagglutinin (PHA) and treated with interleukin-2 (IL-2)) in the presence of inhibitors." (PMID 25329893, 2014). "Given the importance of polyfunctional T cell responses in controlling HIV-1 infection, we measured the ability of multi-clade specific T cell populations from immunized mice to secrete IFN-γ and IL-2 in response to envelope peptide pool stimulation." (PMID 24391921, 2013). "Persistent exposure to antigen, such as occurs in HIV-1 infection, is believed to generate short-lived IFN-γ producing effector memory CD4+ T cells which are impaired in their ability to develop into IL-2 producing central memory cells." (PMID 19352428, 2009). "PI3K inhibitor, added 1 h post-infection of primary mouse T cells, completely blocked HIV-1 infection in the presence of anti-CD3/28 and IL-2." (PMID 18446227, 2008). "IL-7 and IL-2 were previously used to increase CD4+ T cell counts in HIV-1 infection, however, no improvement in their function were reported." (PMID 33384690, 2020).
HIV-1 infection (continued). "During HIV-1 infection, the NK cell repertoire undergoes significant changes, but even in the setting of virological suppression with ART, the NK repertoire remains altered compared to healthy controls in IL-2 activated NK cells." (PMID 32477342, 2020). "Our observation that γc cytokines, specifically IL-2, IL-7, IL-15, and IL-21 were potent inducers of Tim-3 expression on T cells in the antigen-independent manner in HBV infection were consistent with the role of these cytokines in HIV-1 infection." (PMID 28401068, 2017). "In a SIV animal model, IL-2 treatment resulted again in Treg expansion but also promoted CD4+ T cell activation and spontaneous apoptosis, further highlighting the difficulties of using IL-2 in vivo to modulate the course of HIV-1 infection." (PMID 24498287, 2014). "Apart from their intrinsic susceptibility, CD4 + T cells’ activation in vivo (during the natural courses of HIV-1 infection) and in vitro (typically with PHA/IL-2 stimulation) is generally recognized as an absolute prerequisite for the virus to replicate productively." (PMID 23635305, 2013). "Since MIRA CD8+ T cells produce neither IFN-γ nor IL-2, it can be suggested that due to their limited effector function they do not contribute to hyperactivation in chronic HIV-1 infection." (PMID 20598119, 2010). "Combined RemuneTM and IL-2 with ART in advanced HIV-1 infection conferred no immunological benefits to ART." (PMID 17428345, 2007). "Therefore, it was not a surprise that on the day 10–14 of HIV-1 infection in the presence of IL-2 a substantial number of cells, carrying specific NK marker CD56, was detected." (PMID 26692894, 2015). "T cells that produce multiple factors simultaneously (e.g. TNF-α, IL-2 and IFN-γ) are termed polyfunctional T cells and have been shown to provide protection against diseases in murine models of Leishmaniasis and TB, control of hepatitis C and HIV-1 infection and possibly vaccine-induced immunity." (PMID 24959834, 2014). "Detectable virus-specific CD4+ T cell cytokine responses in HIV-1 infection consist mainly of IFN-γ, whereas in subjects able to control viral replication CD4+ T cells that secrete IL-2 are also detectable, and may be a key component of an effective immune response." (PMID 19352428, 2009). "Treatment with anti-CD28 or IL-2 was neither necessary nor sufficient for enhanced HIV-1 infection." (PMID 18446227, 2008). "Furthermore, by knocking down the expression of IL-2, we found that the let-7i-mediated CD4+ T cell resistance to apoptosis during HIV-1 infection was dependent on IL-2 signaling rather than an alternative CD95-mediated cell-death pathway." (PMID 27145859, 2016).
myeloma (58 papers, 1989 to 2025). "High expression of IL-2 is positively correlated with the survival period of multiple myeloma patients." (PMID 38967887, 2024). "NK cells activated with IL-2 and IL-15 are efficient killers of MM cell lines and autologous myeloma cells." (PMID 39538354, 2024). "It is worth mentioning that the therapeutic use of IL-2 together with TNF-α has been shown to influence the elimination of the tumour in a mouse model of myeloma, emphasizing the importance of IL-2 in anti-cancer therapy." (PMID 33808304, 2021). "In vitro studies have shown that the γδ lymphocytes generated after treatment with IL-2 and bisphosphates are effective in killing myeloma plasma cells." (PMID 33808304, 2021). "We designed a phase II clinical trial to evaluate the treatment with IL2 and zoledronate after autologous bone marrow transplantation in myeloma patients." (PMID 33613510, 2020). "WB collected from healthy donors (HDs) and patients with multiple myeloma (MM) was stimulated with P815-ULBP1+CD48 cells combined with IL-2." (PMID 33143099, 2020). "Our schedule of IL2 and zoledronate is feasible in myeloma patients after autologous bone marrow transplantation and results in a median TTP of 22.5 months in patients that achieved VGPR." (PMID 33613510, 2020). "The maintenance treatment with IL2 and Zoledronate has a modest activity in myeloma patients after autologous bone marrow transplantation." (PMID 33613510, 2020). "Ex vivo γδ lymphocytes, expanded with IL2 and bisphosphonates, efficiently kill myeloma plasma cells in vitro." (PMID 33613510, 2020). "IL‐2 and phosphostim stimulate in vitro expansion of γδ T cells which are efficient in killing of human myeloma cells." (PMID 32480431, 2020). "In our study, we demonstrated that NK cells activated with IL-2 and IL-15 were able to efficiently kill multiple myeloma cell lines and autologous myeloma cells." (PMID 30542346, 2018). "Following administration to multiple myeloma patients, NK cells ex vivo expanded with K562-mb15-4-1BBL and high-dose IL-2 exhibit high CD56 expression and proliferate extensively." (PMID 29456538, 2018). "Addition of the anti-IL-2 mAb to either elotuzumab or elotuzumab plus lenalidomide-treated co-cultures significantly decreased myeloma cell killing compared with control." (PMID 25287778, 2015). "The functional consequences of blocking the receptor were the accumulation of IL-2 in the co-culture supernatants and reduced killing of myeloma cells in the cultures." (PMID 25287778, 2015). "Inhibition by HLA-class I and HLA-E was also observed with IL-2-activated NK cells and at low oxygen levels (0.6 %) mimicking hypoxic bone marrow niches where myeloma cells preferentially reside." (PMID 25920521, 2015). "As the myeloma microenvironment exhibits hypoxic regions, we also determined degranulation of IL-2-activated NK cell subsets at physiologically relevant hypoxic culture conditions of 0.6 % O2." (PMID 25920521, 2015). "We recently showed that IL-2 activation is required for NK cell anti-myeloma responses in clinically relevant hypoxic conditions." (PMID 25920521, 2015). "More importantly, these expanded NK cells reduced myeloma burden in immunodeficient mice, and expanded in vivo in an IL-2 dependent fashion." (PMID 23724099, 2013). "Hypoxia abolishes the killing potential of NK cells against multiple myeloma, which can be restored by IL-2 activation." (PMID 23724099, 2013). "That NK cells activated with IL-2 at 21% O2 are potent at killing hypoxic myeloma cells was also observed for RPMI-8226/S and L-363." (PMID 23724099, 2013). "Campbell and colleagues reported that myeloma cell lines suppress the proliferation of T lymphocytes, blocked in G1 arrest and refractory to respond to IL-2." (PMID 24489445, 2013). "Recently, it has been shown that autologous NK cells from myeloma patients expanded ex vivo with IL-2 displayed significant cytotoxic activity against primary autologous plasma cells." (PMID 22649466, 2012).
myeloma (continued). "Dose-dependent inhibitory effect of monoclonal IgG on NK cell activity was significantly stronger in patients with active myeloma than in normal controls, but exogenous IL-2 could overcome this effect." (PMID 39538354, 2024). "Furthermore, elotuzumab has been shown to enhance NK cell activation and myeloma cell killing through interleukin-2 (IL-2) and tumor necrosis factor alpha (TNF-α) pathways." (PMID 38966176, 2024). "Interestingly, a study was conducted on treatment with IL2 and zoledronic acid as a maintenance therapy after autologous transplantation in patients with multiple myeloma." (PMID 36648882, 2023). "Beyond the direct targeting of HIF-1α, IL-2 activation can also restore the killing potential of NK cells that have been exposed to hypoxia, allowing for maintained degranulation in response to target multiple myeloma cells, despite hypoxic conditions." (PMID 36980629, 2023). "IL-2 is critical to NK activation, can rejuvenate exhausted NK cells, and restores or preserves their cytotoxic potential in response to various stressors or following exposure to multiple myeloma." (PMID 36980629, 2023). "IgA could activate the immune function by modulating the production of key cytokines such as TNF, IL-6, and IL-2 by human myeloma cells." (PMID 37050214, 2023). "In addition, other cytokines related to myeloma biology, including interleukins 2, 6, 17 (IL-2, IL-6, IL-17) can modulate Τregs function." (PMID 34640606, 2021). "In conclusion, our results suggest that IL2 and zoledronate may have activity against myeloma possibly through the activation of γδ lymphocytes." (PMID 33613510, 2020). "IL2 and a synthetic agonist (posphostym) can expand, by one hundred-fold, γδ T-cells which retain an efficient and stable ability to kill plasma cell lines and primary human myeloma cells." (PMID 33613510, 2020). "Therefore, we decided to design a phase II clinical trial to assess the efficacy of the maintenance treatment with IL2 and zoledronate in myeloma patients after autologous bone marrow transplantation." (PMID 33613510, 2020). "Moreover, the reinfusion of autologous IL2 activated lymphocytes has been successfully evaluated in myeloma mouse models." (PMID 33613510, 2020). "In patients with non-Hodgkin's lymphoma or multiple myeloma, systemic administrations of both pamidronate with IL-2 were tolerated by patients and induced expansions of endogenous peripheral Vγ9Vδ2 T cells, accompanied by partial remissions of cancer in some patients." (PMID 32528477, 2020). "Several other immune cells could contribute to the anti-myeloma activity of IL2 and zoledronate treatment and our data cannot exclude their importance." (PMID 33613510, 2020). "Wilhelm and colleagues were the first to demonstrate that activation of Vγ9Vδ2 T cells with pamidronate and low-dose interleukin 2 (IL-2) could induce clinical responses in patients with B-cell lymphomas and multiple myeloma (MM)." (PMID 30013559, 2018). "It was reported previously that IL-2 inhibits tumor formation suggesting that the IL-2-mediated suppression of tumors might be a new approach for treating myeloma or other malignancies." (PMID 28894755, 2017). "However, addition of IL-2 to elotuzumab in the co-cultures in the presence of either PBL or purified NK cells resulted in dose-dependent myeloma cell killing and NK cell activation as determined by CD25 and CD54 upregulation (data not shown)." (PMID 25287778, 2015). "TNF-α, IFN-γ, and IL-2 are important inflammatory cytokines that influence NK cell activation and may have direct cytotoxic effects on myeloma cells." (PMID 25287778, 2015). "Although cereblon is essential for lenalidomide-mediated direct tumoricidal activity against myeloma, it also mediated T cell activation by lenalidomide or its analogues because knockdown of cereblon in primary human T cells abrogates drug-induced IL-2 expression." (PMID 26447613, 2015).